BRCA1 (BRCA1 DNA repair associated)
Diseases named in the same sentence as BRCA1 in open-access papers (continued):
Sharing a sentence is not in itself a finding about the gene and the disease.
ovarian carcinoma (continued). "CDK12, which promotes transcription in several HR pathway genes, such as BRCA1, is one of the most frequently mutated genes in ovarian cancer." (PMID 34711195, 2021). "Epithelial ovarian cancer accounts for 85–90% of all ovarian cancers and is the most common type of ovarian cancer with unique genomic characteristics such as mutations in BRCA1 and BRCA2 that encode proteins involved in DNA damaged repair." (PMID 34631788, 2021). "At the same time, risk-reducing mastectomy and contrast-enhanced breast MRI surveillance for BRCA1/2 mutation carriers developing breast or ovarian cancer are also covered by insurance." (PMID 34674065, 2021). "The highest frequency of tested mutations in ovarian cancer patients was detected for the BRCA1 gene." (PMID 33670479, 2021). "The cumulative risk of developing ovarian cancer by age 80 years is 44% for BRCA1 and 17% for BRCA2 carriers." (PMID 33922503, 2021). "In concordance, among young patients with ovarian carcinoma who are below 40 years of age, 22% are BRCA1 mutation carriers." (PMID 34944094, 2021). "So far, few studies have been focused on understanding the differences in transcriptome and functional landscapes associated with the disease (breast vs. ovarian cancers), gene (BRCA1 vs. BRCA2), and mutation type (germline vs. somatic)." (PMID 33525353, 2021). "Carriers of germline pathogenic variants (PVs) in BRCA1 or BRCA2 have a high lifetime risk of ovarian cancer, in particular high‐grade serous pathology." (PMID 33152107, 2021). "Among patients with ovarian cancer, the retention rate of BRCA1/2 mutation was 8.3–14.7% (BRCA1: 3.4–9.9%, BRCA2: 4.7–5.3%)." (PMID 32862296, 2021). "Concerning the BRCA1-mutated ovarian cancers, an equal percentage of mutations were located either within exons 11–13 (45.7%) or in the BRCT domain (45.7%)." (PMID 34898566, 2021). "Somatic CDK12 mutations or chemicals that disable CDK12 function in ovarian cancer cells reduce BRCA1 levels, disrupt HR repair, and sensitize these cells to platinum." (PMID 34645978, 2021). "At present, the only proven way to minimise the risk of ovarian cancer in the carriers of pathogenic variants in BRCA1/BRCA2 is prophylactic bilateral salpingo-oophorectomy." (PMID 34771713, 2021). "The emergence of PARP inhibitors brought new hope, but only 10-20% of patients with ovarian cancer carry BRCA1/2 mutations, and the need for a first-line maintenance treatment has not been met." (PMID 34919531, 2021). "We recommend that in Poland all women with ovarian cancer and first-degree female relatives should be tested for the panel of 18 founder mutations in BRCA1, BRCA2, PALB2, and RAD51C." (PMID 33670479, 2021). "Since the 2007 recommendation, newer research also shows that individuals with ovarian cancer have pathogenic variants in genes other than BRCA1/2, and NCCN updated its guideline in 2016 to recommend a gene panel." (PMID 34834546, 2021). "The results of our study are concordant with previously reported analyses which show a high prevalence of BRCA1/2 mutations among ovarian cancer patients with dominant founder/recurrent population-specific mutations located in BRCA1." (PMID 33670479, 2021). "BRCA1/2 gene mutation status is widely known to result in reduced genome integrity, thus greatly increasing risk of breast and ovarian cancer development." (PMID 34209669, 2021). "For instance, olaparib treatment induced a strong antitumour immune response in different pre-clinical tumour mouse models, including TNBC, SCLC and BRCA1-deficient ovarian cancer, in a cGAS/STING-dependent manner." (PMID 34885119, 2021). "Olaparib is the first US Food and Drug Administration (FDA)-approved PARP inhibitor for use in treating advanced ovarian cancer with germline BRCA1/2 mutations." (PMID 34830749, 2021). "Emerging evidence has revealed that BRCA1 mutations in breast and ovarian cancers are more sensitive to PARP inhibitors." (PMID 34830749, 2021).
ovarian carcinoma (continued). "Risk-reducing surgery among individuals with BRCA1/2 pathogenic variants is associated with reductions in breast and ovarian cancer of 85–100% and 69–100%, respectively." (PMID 34834546, 2021). "The prevalence of ovarian cancer among women with PVs in these moderate penetrance ovarian-cancer risk genes was similar to BRCA1, where 13.7% (975/7114) of BRCA1 PV carriers had a personal history of ovarian cancer." (PMID 33926482, 2021). "More specifically, patients have a 44% and 17% lifetime risk for ovarian cancer with germline mutant BRCA1 and BRCA2, respectively." (PMID 33391401, 2021). "Compared to the normal population risk of about 1.4%, BRCA1 mutation carriers have an estimated 40% risk of developing ovarian cancer by age 70, while this risk is up to 18% for BRCA2 mutant individuals." (PMID 33435590, 2021). "In this work, we set the objectives to evaluate the prevalence of pathogenic BRCA1/2 germline and somatic mutations patients with ovarian cancer in population of Portsmouth, UK, and to evaluate the usefulness and serviceability of tBRCA1/2 mutations analysis." (PMID 33808557, 2021). "The role of PAF and its receptor in BRCA1-mutated ovarian cancer cells has also been examined in other studies." (PMID 34571986, 2021). "In the scenario of Brazilian ovarian cancer patients, for whom BRCA1/BRCA2 mutation frequency is 20%, performing genetic testing and adopting prophylactic measures for family members was considered a cost-effective measure." (PMID 34287479, 2021). "For ovarian cancer, mutations in the homologous recombination (HR) repair genes BRCA1 and BRCA2 are the most common alterations and inhibitions of the DDR pathway protein poly(ADP ribose) polymerase (PARP)." (PMID 34712221, 2021). "Previous studies have indicated that ovarian cancer subtypes with higher BRCA1 mutations correspond to environments with higher expression levels of immune checkpoint molecules and elevated levels of infiltrating immune cells, consistent with our results." (PMID 34306015, 2021). "This study demonstrated that ovarian cancer patients with mutated BRCA1/2 had a four-fold increased risk of developing brain metastases and were diagnosed with brain metastases approximately 8 months earlier than patients with wild-type BRCA1/2." (PMID 35008272, 2021). "Breast cancer susceptibility gene 1 (BRCA1) is responsible for hereditary breast and ovarian cancers." (PMID 33888730, 2021). "Little is known about how women with a BRCA1/2 mutation develop an individual understanding of their breast and ovarian cancer risk and how this affects their psychological distress." (PMID 34069035, 2021). "Approximately one-half of ovarian cancers harbor homologous recombination deficiencies (HRDs), and BRCA1/2 mutations account for half of these deficiencies." (PMID 34919531, 2021). "We performed BRCA1/2 mutation centered RNA-seq data analysis of breast and ovarian cancers from the TCGA repository using transcriptome and phenotype “portrayal” with multi-layer self-organizing maps and functional annotation." (PMID 33525353, 2021). "Approximately 75% of women with hereditary breast and ovarian cancers have germline BRCA1 mutations (gBRCA1), and 10–20% have germline BRCA2 (gBRCA2) mutations." (PMID 33808557, 2021). "Studies regarding the direct testing of BRCA mutations and variants showed that these mutations marked increase ovarian cancer with SIR values of 139.12 (BRCA1) and 74.93 (BRCA2), whereas the effects in other cancers mostly have SIR values of around 1–2." (PMID 34577828, 2021). "Female BRCA1 germline mutation carriers have a cumulative risk of 44% to develop ovarian cancer before the age of 80 years." (PMID 33480862, 2021). "Approximately 10–15% of epithelial ovarian cancer is caused by a germline mutation in the BRCA1 or BRCA2 gene." (PMID 34069790, 2021).
ovarian carcinoma (continued). "Novobiocin synergistically increased the cytotoxic effects of the PARP inhibitors rucaparib and olaparib in BRCA1-deficient human retinal pigment epithelial cells and ovarian cancer cell lines, respectively." (PMID 35198436, 2021). "BRCA1 deficiency was shown to promote BECLIN 1-dependent autophagy that protected ovarian cancer cells (and benign ovarian epithelial cells) from toxic metabolic stress." (PMID 33670664, 2021). "A large number of risk factors for developing epithelial ovarian cancers have been identified, including a family or personal history of breast or ovarian cancer, gene alterations (e.g., BRCA1/2), reproductive history, and advanced age." (PMID 34216135, 2021). "Germline mutations in tumor suppressor gene BRCA1 are highly penetrant for the increased risk of familial breast and ovarian cancer occurrence 4-6." (PMID 34421362, 2021). "Pathogenic or likely pathogenic germline BRCA1 or BRCA2 variants are present in 18% of ovarian cancer cases." (PMID 34711195, 2021). "The BRCA1/BRCA2 reversion mutations in cfDNA were found by sequencing analysis from 21% of therapy-resistant of ovarian cancer patients." (PMID 33936202, 2021). "Numerous studies have indicated that the risk of ovarian cancer was related to BRCA1 and BRCA2 genes." (PMID 33391423, 2021). "Potential use of PAF-AH as a biomarker for predicting the disease risk of BRCA1 mutation carriers and for the prognosis of patients with BRCA1-negative ovarian cancer should be explored." (PMID 34206491, 2021). "The most important genetic causes of ovarian cancer are mutations in BRCA1 and BRCA2 genes, which account for up to 15% of all cases." (PMID 33670479, 2021). "In Barbados, 18% of patients with breast and ovarian cancer had a germline variant with only 1 recurrent, pathogenic variant in BRCA1, which was found in 4 unrelated individuals." (PMID 33646313, 2021). "Our findings support several assumptions of the CSM applied to women with a BRCA1/2 mutation, illustrating how these individuals cope with an increased breast and ovarian cancer risk." (PMID 34069035, 2021). "The aim of this audit was to evaluate the usefulness and serviceability of testing for pathogenic mutations in BRCA1 or BRCA2 (BRCA1/2) genes in ovarian cancer (OC) patients." (PMID 33808557, 2021). "In high-grade serous ovarian cancer, BRCA1/BRCA2 gene mutations are important players in the HR pathway and account for 20% of patients with ovarian cancer with BRCA1/BRCA2 somatic or germline mutations." (PMID 34712221, 2021). "Germline mutations in BRCA1 are responsible for a considerable proportion of hereditary breast and ovarian cancers." (PMID 33767581, 2021). "Breast cancer susceptibility gene 1 (BRCA1) encodes a tumor suppressor that is frequently mutated in familial breast and ovarian cancer patients." (PMID 34421362, 2021). "A genetic predisposition of ovarian cancer is frequent: previous studies have shown that 13–20% of unselected ovarian cancer patients carry a pathogenic BRCA1/2 variant." (PMID 34082720, 2021). "The rs2304277 variant in the OGG1 glycosidase gene of the base excision repair pathway has been shown to increase the penetrance of ovarian cancer in patients with BRCA1/2 mutations." (PMID 33541411, 2021). "For example, prophylactic mastectomy and prophylactic oophorectomy have been proven to be effective in preventing most breast and ovarian cancer in BRCA1‐ and BRCA2‐associated hereditary breast and ovarian cancer syndrome (Petrucelli, Daly, & Pal, 2016)." (PMID 33350578, 2021). "Some of the genetic risk factors for ovarian cancer include mutations in the tumor suppressor genes BRCA1 and BRCA2." (PMID 33910165, 2021). "Response to platinum is a hallmark feature of HR-deficient cancers such as germline mutated BRCA1/2 breast and ovarian cancers." (PMID 34696429, 2021). "Firstly, BRCA1 pathogenic variants carry a higher lifetime risk of ovarian cancer occurring over a decade earlier than BRCA2-associated ovarian cancers." (PMID 34627117, 2021).
ovarian carcinoma (continued). "Among the 54 women with ovarian cancer and a BRCA1 mutation, only 28 reported a first- or second-degree relative with breast or ovarian cancer (50.9%)." (PMID 33478551, 2021). "Female carriers of pathogenic variants in BRCA1/2 have a high lifetime risk of breast and ovarian cancer." (PMID 33836815, 2021). "Different from other tumor suppressor genes with both germline and somatic mutations, there are rare somatic mutations in the BRCA1 gene in breast and/or ovarian cancers." (PMID 34926299, 2021). "BRCA1 mutation carriers are thus more likely to develop ovarian cancer than BRCA2 mutation carriers, as previously reported." (PMID 34680878, 2021). "Cyclin-dependent kinase 12 (CDK12) is also one of the only nine significantly mutated genes in ovarian cancer (3% of cases in the TCGA dataset) and is known to promote the transcription of several HR pathway genes, including BRCA1." (PMID 35052761, 2021). "Expectedly, regarding HBOC-related tumors in the family of probands carrying a pathogenic BRCA1/2 variant, breast and ovarian cancer were more frequent before the age of 50 years, and irrespective of age as well." (PMID 33672545, 2021). "BRCA1 mutations are almost exclusively associated with female breast and ovarian cancer, whereas BRCA2 families are also at risk for male breast cancer, pancreatic cancer in both males and females, and prostate cancers." (PMID 33922503, 2021). "In 23 ovarian cancer patients with detectable P/LP variants, BRCA1 and BRCA2 accounted for 13 (56.5%) patients." (PMID 33649982, 2021). "Women who inherit BRCA1/2 mutations have a lifetime risk to develop breast and ovarian cancer of 45-60% and 10-59%, respectively." (PMID 34552867, 2021). "Fifteen to 25% of patients with ovarian cancer have a germline BRCA1/2 mutation, whereas the other 75-85% are BRCA1/2 wildtype 12." (PMID 33391401, 2021). "We found that approximately 25.2% (54 patients) of unselected cases of ovarian cancer carried one of only six founder mutations in the BRCA1 or BRCA2 gene." (PMID 33478551, 2021). "Our study shows an association between olaparib plasma exposure and toxicity in patients treated for BRCA1/2 mutated ovarian cancer." (PMID 34451901, 2021). "Contrariwise, it has been recently shown that breast and ovarian cancer risks differ depending on the position and the type of BRCA1 and BRCA2 mutations meaning challenges regarding their structure and function." (PMID 34456966, 2021). "The corresponding ovarian cancer risks were 14% (95% CI, 2% to 24%), 33% (8% to 50%), and 20% (2% to 35%) in carriers of the 185delAG, 5382insC in BRCA1 and 6174delT mutations in BRCA2, respectively." (PMID 34356066, 2021). "These compounds inhibited not only RAD52, but also the growth of BRCA1/2-deficient cells, typical for hereditary breast and ovarian cancers." (PMID 33671579, 2021). "A family history of cancer, age, and repeated ovulation with mutation in BRCA1 are associated with ovarian cancer." (PMID 34721577, 2021). "Women who carry a BRCA1/2 germ line mutation face a high lifetime risk for the development of breast and ovarian cancer." (PMID 34070748, 2021). "Women carrying a BRCA1/2 mutation live with a substantially elevated lifetime risk of developing breast and ovarian cancer." (PMID 34069035, 2021). "Hereditary breast and ovarian cancer (HBOC) syndrome is a susceptibility syndrome for cancers, such as breast and ovarian cancer, and BRCA1/2 are its causative genes." (PMID 34674065, 2021). "Compared to the lifetime risk of developing breast (12.9%) and ovarian cancer (2.7%) in the general population, female carriers of pathogenic BRCA1 mutations are at a significantly higher risk of developing these cancers." (PMID 35008272, 2021).
ovarian carcinoma (continued). "The BOADICEA model was originally developed to predict the risks of developing breast and ovarian cancer on the basis of BRCA1 and BRCA2 mutations and explicit cancer family history." (PMID 34199804, 2021). "The cumulative lifetime ovarian cancer risk was estimated to be 36.9% (95% CI: 23.4–53.9%) for BRCA1 and 14.9% (95% CI: 7.4–28.5%) for BRCA2 carriers." (PMID 34063308, 2021). "Through years of building on this concept both preclinically and clinically, PARPi have received FDA approval to treat both breast and ovarian cancers carrying germline BRCA1/2 mutations." (PMID 33470989, 2021). "Of variant carriers, 13.2% (19 of 144, all BRCA1) had a second cancer in the contralateral breast or ovarian cancer." (PMID 33646313, 2021). "In accordance with our findings, it was shown also that the occurrence of both breast and ovarian cancer in a woman is associated with a high likelihood of a germline BRCA1 mutation." (PMID 34490083, 2021). "Consistently, BRCA1 deficient ovarian cancer cells were highly dependent on BECLIN 1-dependent autophagy for survival, and rapidly underwent cell death upon autophagy disruption." (PMID 33670664, 2021). "Similar to other studies, we also observed BRCA1 mutations occurring more frequently than BRCA2 mutations in Chinese ovarian cancer patients." (PMID 35070965, 2021). "Multivariate analysis showed an increase in ovarian cancer risk associated with use of HRT for BRCA1/2 mutation carriers (OR = 1.98; 95% CI 1.21–3.25)." (PMID 33885953, 2021). "In many mutational analyses of BRCA1/2 genes for epithelial ovarian cancer, we picked up large-scale epidemiological studies of more than 500 ovarian cancer patients." (PMID 34356066, 2021). "Five to ten percent of breast and ovarian cancers are hereditary mainly due to pathogenic variants in the susceptibility genes, BRCA1 and BRCA2, transmitted in an autosomal dominant mode." (PMID 34202044, 2021). "The B,D-dilactam steroidal alkylator ASA-B presented a more clear synthetic lethality attribute in BRCA-1 mutated UWB1.289 ovarian cancer cells due to its corresponding cytostatic and cytotoxic effects in relation to its inhibitory activity on PARP enzymes." (PMID 34440232, 2021). "The germline carrier of the BRCA1 pathogenic mutation has been well proven to confer an increased risk of breast and ovarian cancer." (PMID 33477375, 2021). "Approximately 50% of epithelial ovarian cancers exhibit DNA repair defects through homologous recombination, and BRCA1/2 mutations in germline and somatic cells are the most common mechanism underlying homologous recombination deficiency." (PMID 34836507, 2021). "These moderate penetrance genes are associated with lower lifetime risks of ovarian cancer than BRCA1 and BRCA2, but still confer significantly increased risk compared to the general population, with lifetime risks ranging from 6 to 15%." (PMID 33926482, 2021). "Another study also displayed that the HRD score in ovarian cancer with BRCA1/2 mutations tended to be higher in the recurrent than in the primary sample." (PMID 34869593, 2021). "In this study, we identified and characterized, for the first time, a tandem triplication of the BRCA1 5′ end concerning exons 1 and 2 and part of intron 2 in high-risk breast/ovarian cancer families." (PMID 34202044, 2021). "It is needed to further study and verify the role of BRCA1/BRCA2 reversion mutations in ovarian cancer." (PMID 33936202, 2021). "It should be noted that the incidence of ovarian cancer and the percentage of cases of carrier-induced BRCA1 or BRCA2 mutations are among the highest in the world." (PMID 33478551, 2021). "Frequency of pathogenic variants in BRCA1 and 2 genes, other high and moderate penetrance genes in various high-risk categories of patients with breast and/or ovarian cancer." (PMID 34326862, 2021). "For example, prostate or ovarian cancer patients with germline mutations in BRCA1/2, which implies DDR deficiency, response well to PARP inhibitors." (PMID 34926252, 2021).